PATZ1 (POZ/BTB and AT hook containing zinc finger 1)
Diseases named in the same sentence as PATZ1 in open-access papers (continued):
Sharing a sentence is not in itself a finding about the gene and the disease.
thyroid cancer (continued). "Immunohistochemistry on clinical specimens revealed that PATZ1 nuclear expression was less frequent in thyroid cancers than that in the normal thyroid gland and hyperplasia." (PMID 29137300, 2017). "When PATZ1 was silenced in differentiated thyroid cancer (DTC) cell lines (TPC-1 and FTC-133), proliferation, cellular motility, and expression of uPA and MMPs were significantly increased." (PMID 29137300, 2017). "Our present study provides clear evidence that PATZ1 is involved in the regulation of the expression of uPA and MMPs during the process of carcinogenesis and progression of thyroid cancer." (PMID 29137300, 2017). "We demonstrated that PATZ1 is involved in the transition of normal thyroid follicular epithelial cells to malignant phenotype as well as in the dedifferentiation of thyroid cancer cells by altering the expression of proteolytic enzymes." (PMID 29137300, 2017). "Consistently, the restoration of PATZ1 expression in dedifferentiated thyroid cancer cells inhibited their malignant behavior both in vitro, including their capacity to migrate and invade, and in vivo, including a partial re-differentiation." (PMID 29186807, 2017). "Consistent with their study, we found that PATZ1 nuclear expression was less frequent with the progression of thyroid cancer, while, as expected, PATZ1 localized in the nucleus of epithelial cells in normal thyroid tissue and hyperplasia." (PMID 29137300, 2017). "In thyroid cancer, the degree of downregulation further increases proceeding from differentiated to undifferentiated carcinomas, suggesting a PATZ1 role in thyroid cancer progression." (PMID 29186807, 2017). "Then, we confirmed the tumour suppressor activity of PATZ1 in thyroid cancer since the restoration of its expression in the Ras-transformed thyroid cells significantly decreased cell proliferation and migration." (PMID 27125250, 2016). "All together these functional assays confirm that restoration of PATZ1 expression is able to decrease both proliferation and migration of thyroid transformed cells as already described in human thyroid cancer cells." (PMID 27125250, 2016). "The aim of the present work was to elucidate the upstream signalling mechanisms regulating PATZ1 expression in thyroid cancer cells." (PMID 27125250, 2016). "The expression of PATZ1 gene was analyzed, by quantitative RT-PCR (qRT-PCR), in human thyroid cancer cell lines and tissues compared to normal thyroids (NT)." (PMID 25595894, 2015). "In this study we have analyzed PATZ1 expression and function in human thyroid cancer, identifying a potential tumor suppressor role in this type of cancer, mainly involved in inhibition of epithelial-mesenchymal transition (EMT) and cell migration." (PMID 25595894, 2015). "We first analyzed a wide panel of thyroid cancer cell lines and tissues, observing that PATZ1 is expressed at significantly lower levels compared to normal thyroid tissues." (PMID 25595894, 2015). "We demonstrated PATZ1 is down-regulated in thyroid carcinomas compared to normal thyroid tissues, with an inverse correlation to the degree of cell differentiation." (PMID 25595894, 2015). "We have previously shown that PATZ1 counteracts EMT in thyroid cancer cells." (PMID 37046851, 2023). "Consistent with previous results in xenografts from PATZ1 expressing human thyroid cancer cells, PATZ1 expression tends to be lost even in tumors derived from PATZ1 overexpressing cells and is mainly observed in tumor areas characterized by follicular-like structures." (PMID 30744101, 2019).
thyroid cancer (continued). "Restoration of PATZ1 expression in human thyroid cancer cells partially reverts their malignant phenotype, whereas its silencing induces malignant transformation of normal thyroid cells, thus confirming a tumor suppressor role for PATZ1 in thyroid carcinogenesis." (PMID 30744101, 2019). "Indeed, a tumor suppressor role has been demonstrated for PATZ1 in vitro and in vivo by using human thyroid cancer, normal cells, and nude mice transplanted with these cells, respectively, where it counteracts EMT and partially induce the reverse process MET." (PMID 30744101, 2019). "PATZ1 is a transcriptional factor downregulated in thyroid cancer whose re-expression in thyroid cancer cells leads to a partial reversion of the malignant phenotype, including the capacity to proliferate, migrate, and undergo epithelial-to-mesenchymal transition." (PMID 30744101, 2019). "To investigate the cause of the enhanced tumor engraftment of FRTL5-Ras-PATZ1 cells we evaluated whether PATZ1 expression plays a role in thyroid cancer stem biology." (PMID 30744101, 2019). "The observed PATZ1 reduction during thyroid cancer development could be a consequence of an activation of the RET/PTC-RAS-BRAF signaling." (PMID 29584698, 2018). "Therefore, accordingly, we report that both E-cadherin and PATZ1 expression are absent in all PDTCs and ATCs developed by these mice, similar to that already described in human thyroid cancer, where PATZ1 expression is downregulated or lost in ATCs." (PMID 29584698, 2018). "The phenotypic analysis of RET/PTC1TG mice intercrossed with Patz1-knockout mice revealed that deficiency of both Patz1 alleles enhanced thyroid cancer incidence in RET/PTC1TG mice, but not the heterozygous knockout of the Patz1 gene." (PMID 29584698, 2018). "Therefore, RET/PTC1TG;Patz1+/− mice show a thyroid cancer phenotype intermediate between that of RET/PTC1TG;Patz1+/+ and RET/PTC1TG;Patz1−/− mice." (PMID 29584698, 2018). "Further analyses of PATZ1 and related molecules may lead to the development of novel therapeutic strategies to prevent the progression of thyroid cancer." (PMID 29137300, 2017). "Moreover, the frequency of positive nuclear PATZ1 expression decreased along with the dedifferentiation of thyroid cancer in clinical specimens." (PMID 29137300, 2017). "From these findings, we hypothesized that PATZ1 might be involved in the early stage of carcinogenesis of thyroid cancer as well as in the late stage of cancer progression." (PMID 29137300, 2017). "In addition, PATZ1 negatively regulated the expression of uPA and these MMPs in thyroid cancer cell lines." (PMID 29137300, 2017). "Western blot analysis indicated that the nuclear PATZ1 expression in Nthy-ori 3-1 cells was higher than that in thyroid cancer cell lines, and the nuclear PATZ1 expression in TPC-1 that originated from DTC was higher than that in the ATC cell lines (ACT-1 and FRO)." (PMID 29137300, 2017). "Our study suggests that PATZ1 might be involved in the oncogenic process of thyroid cancer from its early to late stage." (PMID 29137300, 2017). "In this frame, also a potential role of PATZ1 in thyroid cancer stem cells might be taken in consideration." (PMID 29186807, 2017). "However, in thyroid cancer PATZ1 protein is not only downregulated compared to normal thyroid tissue, but it is also increasingly delocalized from the nucleus to the cytoplasm proceeding from differentiated to undifferentiated thyroid carcinomas." (PMID 29186807, 2017). "Restoration of PATZ1 expression in three thyroid cancer-derived cell lines, all characterized by fully dedifferentiated cells, significantly inhibited their malignant behaviors, including in vitro proliferation, anchorage-independent growth, migration and invasion, as well as in vivo tumor growth." (PMID 25595894, 2015).
thyroid cancer (continued). "All together these results indicate that PATZ1 has a key role in suppressing migration and invasiveness of thyroid cancer cells, but also suggest that this role could involve different aspects of cell migration in different cellular contexts." (PMID 25595894, 2015). "Notably, we showed that PATZ1 is strongly downregulated in all the thyroid cancer cell lines analyzed." (PMID 25595894, 2015). "A similar role could also be suggested for PATZ1 in thyroid cancer." (PMID 30744101, 2019). "Therefore, we suggest that PATZ1 may play a role in enhancing the stem cell potential of thyroid cancer cells, but, at the same time, it impairs the proliferation of non-stem cells." (PMID 30744101, 2019). "Our study demonstrates that PATZ1 knockdown enhances malignant phenotype both in thyroid follicular epithelial cells and thyroid cancer cells, suggesting that PATZ1 functions as a tumor suppressor in thyroid follicular epithelial cells and is involved in the dedifferentiation of thyroid cancer." (PMID 29137300, 2017). "As nuclear PATZ1 expression decreased along with the progression of thyroid cancer both in clinical specimens and cell lines, we tested whether forced expression of PATZ1 by transfection of a vector encoding human PATZ1 could inhibit the transition of cells to a more malignant phenotype." (PMID 29137300, 2017). "Our present study demonstrated that PATZ1 acts as a tumor suppressor in thyroid follicular epithelial cells and plays an indispensable role in the progression of thyroid cancer, suggesting that the function of PATZ1 might depend on cell types in various organs." (PMID 29137300, 2017). "Therefore, the aim of our studies has been to unveil the mechanisms that could regulate PATZ1 expression in thyroid cancer." (PMID 27125250, 2016). "Interestingly, RET/PTC1TG mice heterozygous for the Patz1-knockout mutation do not significantly differ from RET/PTC1TG;Patz1+/+ control mice as far as thyroid tumor incidence is concerned, but their thyroid cancer phenotype is significantly more aggressive than that of controls." (PMID 29584698, 2018). "To determine whether the expression of PATZ1 plays a role in thyroid cancer cell growth, we carried out colony-forming assays in three thyroid cancer cell lines (TPC1, BC-PAP and FRO), transfected with a vector coding for the human PATZ1 variant 4 (HA-PATZ) or the empty vector (pCEFL-HA)." (PMID 25595894, 2015). "Indeed, Patz1-knockout mice develop NSCLC, and overexpression of PATZ1 in NSCLC cells attenuates EMT and inhibits their proliferation, migration, and invasion, as previously observed in thyroid cancer cells." (PMID 37046851, 2023). "In summary, the spectrum of thyroid malignant neoplasms developed by RET/PTC1TG mice carrying one, two, or no Patz1-null alleles included classical and solid variants of PTC, PDTCs, and ATCs." (PMID 29584698, 2018). "This is consistent with previous results in human thyroid carcinomas, and may explain why we did not observe significant differences in the proliferation index of RET/PTC1TG;Patz1+/− and RET/PTC1TG;Patz1−/− thyroid cancers." (PMID 29584698, 2018). "In the time-window of 10–17 months of age, thyroid carcinomas were present in 100% of RET/PTC1TG;Patz1−/−, whereas they were diagnosed in 54% and 58% of RET/PTC1TG;Patz1+/+ and RET/PTC1;Patz1+/− mice, respectively, that also show the presence of hyperplasia/goiter." (PMID 29584698, 2018). "Interestingly, PATZ1 expression was either reduced or lost in thyroid carcinomas derived by either RET/PTC1TG;Patz1+/+ or RET/PTC1TG;Patz1+/− mice, respectively, compared to normal thyroids or hyperplastic lesions." (PMID 29584698, 2018).
thyroid cancer (continued). "Indeed, we showed here that RET/PTC1WT;Patz1+/− mice develop thyroid carcinomas even with a minor incidence and a longer latency than RET/PTC1TG;Patz1+/− mice." (PMID 29584698, 2018). "However, both RET/PTC1TG;Patz1+/− and RET/PTC1TG;Patz1−/− mice developed a more aggressive thyroid cancer phenotype—characterized by higher Ki-67 expression, presence of ATCs, and increased incidence of solid variants of PTC—than that shown by RET/PTC1TG; Patz1+/+ compound mice." (PMID 29584698, 2018). "It is worth noting that Patz1-knockout mice, previously characterized in a mixed c57BL/6J × 129SvJ genetic background, did not spontaneously develop thyroid carcinomas during their lifespan, while they do with the new mixed FVB/N × c57BL/6J × 129SvJ genetic background." (PMID 29584698, 2018).
glioblastoma (8 papers, 2016 to 2025). The most malignant astrocytic tumor (WHO grade IV). "The histopathological appearance of tumors harboring the EWSR1::PATZ1 fusion is diverse, encompassing entities such as ependymomas, high‐ and low‐grade astrocytomas, glioblastomas, and gangliogliomas." (PMID 39583630, 2024). "This study was aimed at investigating the mechanism of PATZ1 inducing apoptosis through PUMA in glioblastoma." (PMID 35509848, 2022). "In the TCGA database, glioblastoma patients were divided into two groups according to PATZ1 expression (according to median) (PATZ1 high expression group and PATZ1 low expression group), and the survival time of the two patients was analyzed." (PMID 35509848, 2022). "PATZ1 plays a biological regulatory role in inducing apoptosis in glioblastoma, and this regulatory effect is related to PUMA, and the specific mechanism remains to be further explored." (PMID 35509848, 2022). "Overexpressed PATZ1 was transfected to explore its role in inducing apoptosis in glioblastoma cells." (PMID 35509848, 2022). "The results showed that low PATZ1 expression correlates with poor prognosis in glioblastoma patients." (PMID 35509848, 2022). "More recently, PATZ1 was revealed to be a potential prognostic marker for glioblastoma in adult patients." (PMID 31614588, 2019). "One article technically met the inclusion criteria but was excluded because it described a tumor that developed the EWSR1::PATZ1 fusion many years later, at the recurrence as a glioblastoma (GBM), making it unlikely that the fusion was the genetic driver mutation." (PMID 39583630, 2024). "PATZ1 colocalizes intracellularly with PUMA inducing apoptosis through PUMA in glioblastoma." (PMID 35509848, 2022). "While the single most common diagnosis was glioblastoma (GBM), clinical data of the PATZ1-fused tumors showed a better prognosis than typical GBM, despite frequent relapses." (PMID 34417833, 2021). "A similar role for PATZ1 has also been suggested in cancer stem cells (CSC) since it is more highly expressed in stem than non-stem cancer derived cells in glioblastomas (GBM)." (PMID 30744101, 2019).
brain tumor (7 papers, 2017 to 2025). "NEpTs harboring EWSR1::PATZ1 fusions represent an exceptionally rare subgroup of primary brain neoplasms, currently unrecognized by the WHO classification system." (PMID 40575153, 2025). "Recent reports have identified a handful of pediatric brain tumors displaying a fusion of the PATZ1 gene with either MN1 or EWSR1 as a partner." (PMID 35204463, 2022). "In human brain tumor cells, PATZ1 has been found to be included in SOX2 interactome, and siRNA targeting of PATZ1 increased its sensitivity to apoptotic stimuli in human GBM cell lines resistant to conventional chemotherapy." (PMID 35509848, 2022). "Recent reports on a small number of pediatric brain tumors showing PATZ1 fusions, as well as the detection of further such cases through our ongoing molecular diagnostic studies, prompted us to investigate the properties of these cases in more detail." (PMID 34417833, 2021). "Interestingly, recent reports have identified a handful of pediatric brain tumors displaying a fusion of the PATZ1 gene with either MN1 or EWSR1 as a partner." (PMID 34417833, 2021). "For example, brain tumor PT_E3ADF4ZB harbored oncogenic fusion MN1-PATZ1, where the DNA breakpoint resides in exon 1 of PATZ1 and disrupts the normal splicing acceptor (where all four patients with MN1-PATZ1 in our cohort belong to neo-splicing category)." (PMID 37019972, 2023). "In human brain tumour cells PATZ1 has been found to be included in the SOX2-interactome, and targeting of PATZ1 by siRNA in human GBM cell lines resistant to conventional chemotherapy, increases their sensitivity to apoptotic stimuli." (PMID 28938636, 2017).
lymphoma (7 papers, 2015 to 2025). A malignant (clonal) proliferation of B- lymphocytes or T- lymphocytes which involves the lymph nodes, bone marrow and/or extranodal sites. "However, on the contrary, PATZ1 has also been implicated as a tumor suppressor gene in lymphomas, thyroid and lung cancer." (PMID 33598459, 2021). "To date, the role of PATZ1 in cancer progression has been studied in breast, lung, thyroid, testicular cancers and lymphomas." (PMID 33598459, 2021). "In particular, in one lymphoma (833PA) it was accompanied by overexpression of Bcl6 and in the other one (800PA) by downregulation of Bcl6, indicating a molecular heterogeneity in Patz1-dependent lymphomagenesis, sometime involving BCL6 and more often BAX." (PMID 27494852, 2016). "Recently, we showed that PATZ1-knockout mice develop lymphomas and other neoplasias, indicating PATZ1 as a potential tumor-suppressor in lymphomagenesis and likely other tumors." (PMID 25595894, 2015). "Conversely, it was also demonstrated that mice lacking PATZ1 develop lymphomas and other tumors, suggesting that PATZ1 functions as a potential tumor suppressor in lymphomagenesis and possibly in other cancers." (PMID 41155227, 2025).
hepatocellular carcinoma (6 papers, 2017 to 2024). A malignant tumor that arises from hepatocytes. "Here we report that PATZ1 regulates cell proliferation by directly regulating CDKN1B (p27) in hepatocellular carcinoma cells." (PMID 33598459, 2021).
colon cancer (5 papers, 2016 to 2023). "We also discovered potentially novel modules relating to mitochondrial organization, protein localization, and targets of zinc finger transcription factor PATZ1 to be significantly associated with colon cancer progression." (PMID 36950380, 2023). "For instance, the silencing of the cofactor PATZ1 of KLF4 inhibits the colon cancer cell proliferation." (PMID 28684851, 2017). "The scientists also speculate that PATZ1 may be a potential proto-oncogene for colon cancer, although the precise mode of action has yet to be investigated." (PMID 36358661, 2022). "PATZ1 knockdown dramatically triggered cell cycle arrest by lowering cell cycle protein D1/E1 and raising the p21 expression levels, in addition to its involvement in supporting colon cancer cell proliferation." (PMID 36358661, 2022). "In particular, PATZ1 functions as an oncogene in colon cancer by promoting cell cycle progression." (PMID 33598459, 2021).